ARHGAP26 (Rho GTPase activating protein 26)
Diseases named in the same sentence as ARHGAP26 in open-access papers (continued):
Sharing a sentence is not in itself a finding about the gene and the disease.
glioblastoma (3 papers, 2019 to 2023). The most malignant astrocytic tumor (WHO grade IV). "ARHGAP26 was downregulated in glioblastoma and associated with cell proliferation and migration." (PMID 31004081, 2019). "In glioblastoma, ARHGAP26 acts as an important executive molecule downstream of the integrin complex to promote tumor invasion." (PMID 34716859, 2022). "Studies have shown that the integrin complex CD151-α3β1 significantly promotes the invasion and migration of glioblastoma, and ARHGAP26 is a key molecule downstream of the complex." (PMID 34716859, 2022). "Previous studies showed significantly downregulated ARHGAP26 expression in glioblastoma and myeloid malignancies." (PMID 31004081, 2019). "Interestingly, in human invasive ductal breast cancer and glioblastoma, the putative binding sites of miR-30b-3p and miR-573 in the 3′ UTR of ARHGAP26 transcript are destroyed by the ADAR1 editing activity leading to increased ARHGAP26 expression, cell spreading, and migration." (PMID 37958449, 2023).
leukemia (3 papers, 2006 to 2010). A malignant (clonal) hematologic disorder, involving hematopoietic stem cells and characterized by the presence of primitive or atypical myeloid or lymphoid cells in the bone marrow and the blood. "Among the altered genes, ARHGAP26 and MLLT1 have been associated with leukemia-specific translocations, DDHD2, FGFR1 and PTPN1 have tumor-promoting potential in breast cancer, and CTNNA3 may promote tumor formation in urothelial cancer." (PMID 20428235, 2010).
Parkinson (3 papers, 2023 to 2024). "Importantly, the ARHGAP26 single nucleotide polymorphisms were reported to be associated with AD, Parkinson’s, neuropsychiatric, and cardiovascular diseases." (PMID 38719151, 2024). "Thus, because of the correlating anti-ARHGAP26 autoantibodies, we suggest a diagnosis of atypical DLB according to two fulfilled core features (fluctuating cognition, Parkinsonism) and one positive indicative biomarker, namely confirmed pathological I123 CIT-SPECT." (PMID 39081998, 2023).
heart failure (2 papers, 2010 to 2023). Inability of the heart to pump blood at an adequate rate to meet tissue metabolic requirements. "Thus, our studies provide a strong rationale for a more extensive exploration of the association between Arhgap26 polymorphisms and susceptibility to heart failure, PD, and perhaps other diseases that involve metabolic dysfunction." (PMID 38081847, 2023).
prostate carcinoma (2 papers, 2018 to 2022). A carcinoma that arises from epithelial cells of the prostate gland. "In addition, the correlation between the clinicopathological characteristics of prostate cancer patients and upregulation of ARHGAP26 expression is also worth exploring." (PMID 34716859, 2022). "However, no further in vivo or in vitro studies were conducted to clarify the impact of ARHGAP26 on the phenotype of prostate cancer." (PMID 34716859, 2022).
Anxiety (1 paper, 2022). Intense feelings of nervousness, tension, or panic often arise in response to interpersonal stresses. "While ARHGAP26-IgG/anti-Ca was initially identified in a patient with ACA, this patient had additional symptoms compatible with extracerebellar involvement (severe depression, restlessness, and anxiety)." (PMID 35624318, 2022).
autoimmune encephalitis (1 paper, 2022). Inflammation of the brain secondary to an immune response triggered by the body itself. "Therefore, we hypothesised that cross-reactivity of ARHGAP26-IgG/anti-Ca may render ARHGAP10 an additional immune target in patients with ACA and, possibly, other forms of autoimmune encephalitis associated with ARHGAP26-IgG/anti-Ca seropositivity." (PMID 35624318, 2022). "Here we demonstrate that the majority of ARHGAP26/GRAF-IgG-positive patients with autoimmune encephalitis have antibodies that co-react with ARHGAP10/GRAF2, a protein expressed throughout the CNS." (PMID 35624318, 2022). "We demonstrate that a substantial proportion of patients with ARHGAP26-IgG/anti-Ca-positive autoimmune encephalitis co-react with ARHGAP10." (PMID 35624318, 2022). "We found that serum and CSF IgG from ARHGAP26-IgG/anti-Ca-positive patients indeed co-reacts with ARHGAP10 in a substantial proportion of cases, rendering ARHGAP10 a new target antigen in autoimmune encephalitis." (PMID 35624318, 2022).
Cerebellar atrophy (1 paper, 2018). Cerebellar atrophy is defined as a cerebellum with initially normal structures, in a posterior fossa with normal size, which displays enlarged fissures (interfolial spaces) in comparison to the foliae secondary to loss of tissue. "Due to the lack of post-mortem studies in ARHGAP26-positive patients, the targeted cerebellar regions are unknown, but MRI studies revealed generalized cerebellar atrophy." (PMID 30158896, 2018).
chronic myeloid leukemia (1 paper, 2014). "In chronic myeloid leukemia SNPs in ARHGAP26 and IRF8 showed significant association with an increased risk of CML, however only for the uncorrected p-value." (PMID 24886876, 2014).
cognitive decline (1 paper, 2022). "Later, ARHGAP26-IgG/anti-Ca was reported in patients with limbic encephalitis/cognitive decline or peripheral neuropathy." (PMID 35624318, 2022).
dementia (1 paper, 2023). Loss of intellectual abilities interfering with an individual's social and occupational functions. "Here, we report a case of dementia associated with anti-Rho-GTPase-activating protein 26 (ARHGAP26) autoantibodies, which have never been previously linked to DLB." (PMID 39081998, 2023).
glioma (1 paper, 2015). A benign or malignant brain and spinal cord tumor that arises from glial cells (astrocytes, oligodendrocytes, ependymal cells). "In contrast to a prior report on ELMO1, a regulator of GTPase activation and glioma cell motility, our study suggest that the crosstalk between the CD151-integrin complexes and RTKs converge at ARHGAP26, consistent with its link to the EGFR-mediated cell motility and signaling." (PMID 26377974, 2015).
malaria (1 paper, 2014). Malaria is a serious and sometimes fatal disease caused by a parasite that commonly infects a certain type of mosquito which feeds on humans. "This is also consistent with linkage analyses in mice and genetic studies in humans showing an association of IL3, IL4, IL13, IRF1, and ARHGAP26 with parasitaemia, mild malaria or severe malaria." (PMID 24884991, 2014).
myeloid leukemia (1 paper, 2014). A clonal proliferation of myeloid cells and their precursors in the bone marrow, peripheral blood, and spleen. "In adult myeloid leukemias we found significant associations between the variant allele of PML_rs9479 and decreased AML risk (OR = 0.61 (0.38-0.97), and between variant alleles of IRF8_ rs10514611 and ARHGAP26_rs187729 and increased CML risk (OR = 2.4 (1.12-5.15) and 1.63 (1.07-2.47), respectively)." (PMID 24886876, 2014).
myeloma (1 paper, 2023). "However, the most important result is a significant 54% increase in ARHGAP26 gene expression in the BTZ-resistant U266 myeloma cells that were administered vitamin D and K three times compared to BTZ-resistant cells." (PMID 38201971, 2023). "We selected genes (ARHGAP26, MYH10, PMP2, RFX8, BAMBI, CLEC12b) with significant changes in methylation level to validate their expression using qRT-PCR in U266 myeloma cells." (PMID 38201971, 2023).
neuroblastoma (1 paper, 2021). Neuroblastoma (NB) is the most common solid, extracranial childhood tumor. "NEAT1 acts as a sponge for miR-1277-5p targeting Rho GTPase activating protein 26 (ARHGAP26), resulting in oxidative stress with a reduction of GPx and SOD activities in cells of the neuroblastoma cell line, SK-N-SH." (PMID 33921907, 2021).
neuroendocrine tumours (1 paper, 2013). "Notably, ARHGAP26 has been found to be upregulated in neuroendocrine tumours." (PMID 23320754, 2013).
Obesity (1 paper, 2022). Accumulation of substantial excess body fat. "In ConvR HFD mice liver, 17 genes DNA methylation changes including Ube2l3, Etv5, Lrp1, and Nudt3 were determined related to obesity and 11 genes DNA methylation changes including Exoc312, Mst1r, Prkch, and Arhgap26 were determined related to Type 2 diabetes (T2D) in the previous study." (PMID 35458198, 2022).
psychosis (1 paper, 2023). "The broad spectrum of anti-ARHGAP26 autoantibodies, ranging from cerebellar syndrome to cognitive dysfunction and psychosis, may indicate different regional brain involvement depending on which part of the brain the anti-ARHGAP26 autoantibodies were deposited." (PMID 39081998, 2023).
Stroke (1 paper, 2023). Sudden impairment of blood flow to a part of the brain due to occlusion or rupture of an artery to the brain. "Anti-ARHGAP26 autoantibodies are detected at low frequencies in affective disorders (2.27%) and stroke (2.26%) compared with healthy controls (0.88%)." (PMID 39081998, 2023).
tumor (28 papers, 2006 to 2025). "Understanding the cause of the abnormal expression of ARHGAP26 aids in evaluation of the tumor risk and implementation of pre-intervention." (PMID 34716859, 2022). "With these three new cases, now 50% of all reported ARHGAP26-positive patients had a tumor-association, emphasizing the importance to screen for underlying malignancy." (PMID 30158896, 2018). "Likewise, anti-Ca/ARHGAP26 antibodies are associated with a range of neurological manifestations, and in some cases, have been connected to the presence of an underlying tumor." (PMID 40881707, 2025). "For women, 18 independent pleiotropic SNPs were detected, two of which were novel: rs244468 (PCPASSOC = 7.70 × 10–10), located in ARHGAP26, a gene encoding GTPase activating protein that regulates tumor immunity and inflammation, as well as rs4921915 (PCPASSOC = 3.59 × 10–10), an intergenic variant." (PMID 37644603, 2023). "A significant association was detected between ARHGAP21, ARHGAP26, ARHGAP27, ARHGAP 34, ARHGAP 35, ARHGAP42, and ARHGAP46 and the tumor stages." (PMID 38783033, 2024). "Two private neoepitopes (category T) derived from mutations in the FAT atypical cadherin 4 (FAT4) and Rho GTPase activating protein 26 (ARHGAP26) tumor suppressor genes." (PMID 39840067, 2024). "Tumor metastasis was examined after A2780 or HEY cells stably expressing ARHGAP26 or blank vector were intravenously injected into the tail vein of nude mice." (PMID 31004081, 2019). "The team took tumor and healthy tissue samples from 85 patients and confirmed that reduced levels of ARHGAP26 in the cancerous tissues coincided with an increase in an enzyme involved in protein degradation." (PMID 31004081, 2019). "On the other hand, ARHGAP26 is usually expressed in the cytoplasm of normal tissue cells and some tumor cells." (PMID 30034621, 2018). "In conclusion, testing for anti-Ca/anti-ARHGAP26 should be included in the diagnostic work-up of patients with ACA, and an underlying tumour should be considered in patients presenting with anti-Ca/ARHGAP26 antibody-positive ACA." (PMID 23320754, 2013). "We observed increased 5hmC levels in H3K4me3 regions in genes relating to cell proliferation, such as CDK6 and ZMYND8, and reduced 5hmC levels in H3K4me3 regions in genes that may be related to tumor suppression, such as ARHGAP26 and GLI3." (PMID 37372359, 2023). "Among the genomic biomarkers able to discriminate transformed tumours (hEMT, MES) from the epithelial state, we identified genes that have been previously linked with cell migration, invasion and EMT, such as RB1, VHL, ERBB2, ARHGAP26, PRDM1, APC." (PMID 36774358, 2023). "Next, we investigated the effect of ARHGAP26 on tumor metastasis in vivo." (PMID 31004081, 2019). "Rho GTPase-activating protein 26 (ARHGAP26) is a negative regulator of the Rho family that converts the small GTP-binding protein RhoA (GTP-RhoA) to its inactive GDP-bound form and is a putative tumor suppressor gene associated with cell growth and migration." (PMID 31004081, 2019). "The aneuploidic increases in copy number of genes that may promote tumor formation, including ARHGAP26, GRB10, DDHD2, FGFR1, CTNNA3, PTPN1 and MLLT1 in the apparently stable and karyotypically normal lines HS293 and HS401, are cause for concern." (PMID 20428235, 2010). "Interestingly, researchers also detected other systemic tumors in patients with such neurological diseases who were positive for ARHGAP26 antibodies, suggesting that anti-ARHGAP26 antibodies may be a potential tumor predictor in such patients." (PMID 34716859, 2022). "Collectively, both the in vitro and in vivo results demonstrate that the immunogenic P1 peptide derived from CLDN18 (exon 5)-ARHGAP26 (exon 12) fusion can generate NRT cells with specific and promising cytotoxicity against target tumor cells." (PMID 39164472, 2024).
tumor (continued). "Moreover, it has been reported that circ-ARHGAP26 is closely related to the expression of the tumor marker carbohydrate antigen 19–9 (CA19-9), which may provide evidence for the involvement of circ-ARHGAP26 in the expression and regulation of tumor-related proteins." (PMID 34716859, 2022). "Whole genome sequencing (WGS) analysis of a tumor expressing the CTNND1-ARHGAP26 fusion revealed that g.chr11:57,578,103 (CTNND1 intron 15) was aberrantly fused to g.chr5:142,358,707 (ARHGAP26 intron 11) at the genomic DNA level." (PMID 30361512, 2018). "ARHGAP26 (GRAF) belongs to a family of Rho GTPase activating proteins and is a tumor suppressor acting by negatively regulating RhoA, a small GTP-binding protein with a growth-promoting effect in RAS-mediated malignant transformation." (PMID 24886876, 2014). "The NetMHCpan 4.0 was used to predict potential peptides derived from three CLDN18-ARHGAP fusion types previously reported to be present in tumor samples, including junctions of CLDN18 (exon 5)-ARHGAP26 (exon 12), CLDN18 (exon 5)-ARHGAP26 (exon 10) and CLDN18 (exon 5)-ARHGAP6 (exon 2)." (PMID 39164472, 2024). "Numerous studies have demonstrated that ARHGAP26 expression and involvement in tumorigenesis and tumor progression are not the same in different tumors." (PMID 34716859, 2022). "Anti-Ca/ARHGAP26-associated ACA has been reported both in a paraneoplastic context and in patients with no known tumor at the time of anti-ARHGAP26 testing." (PMID 25498830, 2014). "Our immunohistochemical analysis showed that almost all CLDN18-ARHGAP26 fusion-positive cases expressed CLDN18, about half of which expressed ARHGAP26 in the membrane, which likely reflects the requirement of CLDN18 promoter activity for expression of the fusion protein in tumor cells." (PMID 30034621, 2018).
cancer (17 papers, 2014 to 2024). A tumor composed of atypical neoplastic, often pleomorphic cells that invade other tissues. "ARHGAP26 and FAM53B were found associated with five cancer types, and PIP5K1C, FBP1, and CUL9 were found to be associated with four cancer types." (PMID 37187613, 2023). "In cancer specimens, ARHGAP26 expression was found to be downregulated due to its targeting by miR-30b-3p and miR-573." (PMID 37958449, 2023). "Expression of ARHGAP26 at protein or RNA level has been shown for a multitude of solid tumours and cancer cell lines." (PMID 35624318, 2022). "This review summarizes the biological functions and molecular mechanisms of ARHGAP26 in different tumors, proposes the potential clinical value of ARHGAP26 in cancer treatment, and discusses current issues that need to be addressed." (PMID 34716859, 2022). "For example, an extensive A-to-I RNA editing mediated by ADAR1 on the ARHGAP26 3′UTR increases both RNA and protein expression of ARHGAP26 by abolishing the repressive effects of miR-30b-2p and miR-573 in multiple human cancer cell lines." (PMID 31847302, 2019). "Similarly, in BTZ-resistant cells, we observed hypermethylation in the ARHGAP26 gene, which is involved in tumorigenesis and progression of human cancers." (PMID 38201971, 2023). "The team backed up their hypothesis by observing reduced cancer cell proliferation in mice with high levels of ARHGAP26." (PMID 31004081, 2019). "Cytoplasmic ARHGAP26 immunostaining was observed in both normal and cancer cells." (PMID 30034621, 2018). "This enzyme-led destruction of ARHGAP26 may enable cancer metastasis." (PMID 31004081, 2019). "The most important observation is the hypermethylation of the ARHGAP26 gene in cells treated three times with BTZ, which is involved in tumorigenesis and progression of human cancers." (PMID 38201971, 2023). "ARHGAP26, a GAP regulating the Rho GTPases, plays a crucial role in tumorigenesis and progression of human cancers." (PMID 34716859, 2022).
animal disease (1 paper, 2010). "ARHGAP26 has not previously been described as an autoimmune target in human or animal disease." (PMID 20226058, 2010).
peripheral neuropathy (1 paper, 2022). A disorder affecting the peripheral nervous system. "In addition, 17 further ARHGAP26/anti-Ca-positive patients were reported by the Mayo Clinic in 2020, 15 of whom had subacute progressive cerebellar ataxia and 2 peripheral neuropathy, and several as yet unpublished additional cases were identified in our laboratories over the subsequent years." (PMID 35624318, 2022).
ARHGAP26 also shares sentences with these, for which no sentence is quoted: acute myeloid leukemia (5 papers); ATRX syndrome (2); breast carcinoma (2); dilated cardiomyopathy (2); haematologic disorders (2); neurodegenerative disease (2); neurological diseases (2); adenocarcinoma (1); atherosclerosis (1); autoimmune disease (1); cardiac disease (1); cardiomyopathies (1); cardiovascular diseases (1); cerebellar degeneration (1); Cerebral ischemia (1); depression (1); gastric tumors (1); genetic disease (1); infection (1); invasive breast carcinoma (1); juvenile myelomonocytic leukemia (1); leiomyoma (1); mental retardation (1); mood disorder (1); muscle degeneration (1); muscular dystrophy (1); Myelodysplasia (1); myeloid malignancies (1); myeloproliferative diseases (1); renal cell carcinoma (1).
A further 2 diseases each share a sentence with ARHGAP26 in 1 paper.